MTA1 (metastasis associated 1)
Diseases named in the same sentence as MTA1 in open-access papers (continued):
Sharing a sentence is not in itself a finding about the gene and the disease.
cancer (106 papers, 2004 to 2025). A tumor composed of atypical neoplastic, often pleomorphic cells that invade other tissues. "MTA1 overexpression has been linked to a poor prognosis in malignant tumors, as well as increased invasion and metastasis." (PMID 40660330, 2025). "As a regulator of the chromatin structure, MTA1 interacts with transcription factors to modulate gene expression associated with aggressive cancer phenotypes." (PMID 40565190, 2025). "Recent research has underscored the role of proteins like Focal Adhesion Kinase (FAK), Vascular Endothelial Growth Factor (VEGF), and Metastasis-Associated Protein 1 (MTA1) in driving cancer cell proliferation and survival." (PMID 39355129, 2024). "The metastasis-associated gene MTA1 is a transcriptional repressor with a potential effect on cancer." (PMID 36689059, 2023). "In vitro studies showed that IDH3-a promotes EMT by increasing metastasis associated 1 (MTA1), an oncogene involved in the progression of cancer cells to metastasis, thereby enabling migration and invasion of HCC cells." (PMID 37601653, 2023). "LBP is involved in the innate immune response to bacterial infections and MTA1 encodes a transcriptional coregulator upregulated in numerous cancer types and associated with cancer progression." (PMID 35078996, 2022). "Metastasis-associated protein 1 (MTA1) is a transcriptional co-regulator and is an upregulated protein in cancer, whose expression correlates with cancer development, unfavorable prognosis, and enhanced metastatic potential." (PMID 34039961, 2021). "Although all MTAs have been implicated in cancer progression and metastasis, MTA1 and MTA3 play opposing roles in the EMT process." (PMID 33953349, 2021). "The metastasis-associated gene 1 (MTA1) has been extensively reported as a crucial oncogene, and its abnormal expression has been associated with the progression of numerous cancers." (PMID 33059651, 2020). "Here, we demonstrate that cancer metastasis-associated antigen 1 (MTA1), a well-known oncogenic chromatin modifier, broadly interacts and co-expresses with RBPs across cancers, contributing to cancerous mitosis-related AS." (PMID 32901005, 2020). "Metastasis‐associated protein 1 (MTA1), a putative oncoprotein with pivotal roles in cancer progression and metastasis, was used as a positive control in these assays." (PMID 33377651, 2020). "The metastasis-associated gene 1 (MTA1) is a crucial gene involved in cancer metastasis and is overexpressed in many cancers, including gastric, ovarian, prostate, and breast cancer." (PMID 33059651, 2020). "MTA1 regulates gene expression by functioning as a transcription factor and has been reported associated with cancer progression and poor prognosis." (PMID 32678829, 2020). "MTA1 is regulated by miR-30c and miRNA downregulation is associated with MTA1 upregulation in endometrial and ovarian cancer." (PMID 31217897, 2019). "MTA1 is predominantly a nuclear protein that is one of the most upregulated protein in human cancers, and associated with cancer progression." (PMID 30782165, 2019). "Metastasis associated protein 1 (MTA1) is a component of the NuRD that can induce gene silencing and is often upregulated in several cancers." (PMID 30884859, 2019). "MTA1 is considered as one of the most remarkable indicators associated with cancer progression, aggressive phenotype, and poor prognosis." (PMID 31281798, 2019). "Metastasis-associated gene (MTA) refers to a family of cancer progression-related genes, including MTA1, MTA1s, MTA-ZG29P, MTA2, MTA3, and MTA3L." (PMID 31281798, 2019). "Recent study showed that hsa-miR-30c-5p was downregulated in GC tissues and remarkably related with lymphatic metastasis, and it suppressed the invasion ability of cancer by targeting metastasis-associated protein 1(MTA1)." (PMID 29921304, 2018).
cancer (continued). "Metastasis-associated gene 1 (MTA1), an essential component of the nucleosome remodeling and deacetylase (NuRD) complex, appears to promote cancer progression and metastasis." (PMID 28418915, 2017). "Extension to this analysis to other cancer-types such as brain, lung, ovarian, and bladder also reinforced the notion that high MTA1 and low DNMT3a combination associates with an overall poor patient survival." (PMID 28393842, 2017). "Metastasis-associated protein 1 (MTA1) is a transcriptional regulator and significantly associated with prognosis of patients with cancer." (PMID 28570554, 2017). "One of the crucial chromatin remodeling factors in eukaryotic cells is the metastasis-associated protein 1 (MTA1) - one of the most upregulated oncogenes in human cancer that contributes to cancer progression and metastasis." (PMID 28393842, 2017). "Many studies have implicated Metastasis-associated gene 1 (MTA1) as a pivotal regulator during cancer metastasis." (PMID 26698569, 2015). "The functions and mechanisms of metastasis-associated protein 1 (MTA1) in cancer progression are still unclear due to a lagged recognition of the subcellular localization." (PMID 24970816, 2014). "MTA1 expression has been associated with cancer malignancy in various cancer types, and has been found to increase the metastatic and invasive potential of carcinoma cells." (PMID 24396455, 2014). "MTA1, a metastasis-associated protein, has been extensively researched, especially regarding its role in cancer metastasis." (PMID 25332145, 2014). "Among these, metastasis-associated gene 1 (MTA1) is positively correlated with cancer metastasis in many cancer types." (PMID 24396455, 2014). "MTA1-silencing was observed to result in a prominent loss of function in cancer cells, while overexpression of MTA1 only increased cancerous behaviors to a certain extent." (PMID 24396455, 2014). "Overexpression of the metastasis-associated gene 1 (MTA1) has previously been found to be associated with progression of various cancer types to the metastasis stage." (PMID 24396455, 2014). "MTA1 is a key factor in cancer metastasis, and its overexpression was consistently found to be associated with cancer’s advanced stages, higher malignancy degree, and poorer patient prognosis." (PMID 25332145, 2014). "Metastasis-associated gene 1 (MTA1) has been implicated in the carcinogenesis and metastasis of a variety of human cancers." (PMID 23941622, 2013). "As a metastasis-associated protein, overexpression of MTA1 has been demonstrated in a range of malignant tumors and is strongly associated with cancer cell invasion and migration." (PMID 22537306, 2012). "Metastasis-associated protein 1 (MTA1) has been associated with poor prognosis in several malignant carcinomas." (PMID 22537306, 2012). "In fact, MTA1 has been associated with poor prognosis of many types of cancers." (PMID 40351767, 2025). "The MTA1 protein encoded by metastasis-associated protein 1 (MTA1) is a key component of the ATP-dependent nucleosome remodeling and deacetylase (NuRD) complex, which is widely upregulated in cancers." (PMID 35350571, 2022). "HSF1 may coordinate resistant cancer cell properties through chromatin organization in cooperation with HDACs or other DNA-modifying complexes, such as MTA1, each of which have also been linked to resistance to cytotoxic compounds." (PMID 32331382, 2020). "MTA1 overexpression-induced defective mitotic arrest caused obvious mitotic abnormalities, including chromosome lagging, bridging, misalignment and multipolarized chromosomes in cancer cells." (PMID 32901005, 2020). "Since MTA1 has originally been found to be associated with cancer metastasis, we investigated if IL-17 could promote cancer cell migration using wound healing assays." (PMID 31281798, 2019). "Further it is possible that MTA1-DNMT3a axis may be associated with a potential hypo-methylation of certain, yet-to-be identified, target genes in cancer." (PMID 28393842, 2017).
cancer (continued). "In-spite of significant advances in our understanding of the mechanisms of MTA1 overexpression associated cancer progression, the nature of molecular relationship between the MTA1 chromatin remodeling factor and DNA methyltransferases remains poorly understood." (PMID 28393842, 2017). "Collectively, these data support a central role of MTA1 and MTA1-dependent signaling, including novel MTA1-Akt and MTA1-c-Myc feed-forward loops, as significant drivers of Pten-loss induced prostate tumorigenesis and cancer progression suggesting potential benefits of MTA1-targeting approaches." (PMID 26943043, 2016). "MTA1 is a chromatin remodeling protein, which has been implicated in cancer metastasis." (PMID 25797255, 2015). "However, MTA1 overexpression was unanimously associated with more advanced cancer stages, increased metastasis tendency, and unfavorable outcomes." (PMID 25332145, 2014). "Elevated expression levels of MTA1 are strongly associated with the growth of aggressive endometrial, breast and ovarian cancers, and can be used as a prognosis marker in the progression of human cancers." (PMID 25352341, 2014). "Moreover, the underlying mechanism of MTA1 in cancer promotion remains obscure; the only well-studied mechanism is the function of MTA1 in the nucleus with other components of the nucleosome remodeling deacetylase (NuRD) complex to repress gene transcription." (PMID 24970816, 2014). "Both nuclear and cytoplasmic MTA1 are associated with cancer progression." (PMID 24970816, 2014). "Similarly, Tenascin C and MTA1 which are also associated with invasion and migration of cancer cells were upregulated in 3D vs. 2D 293T cells." (PMID 20615238, 2010). "However, these functions may be associated with different mechanisms because only nuclear MTA1 has been associated with cancer differentiation." (PMID 24970816, 2014). "Although extensive research has explored MTA1’s role in various cancer-related processes, its involvement in VM remains poorly understood." (PMID 40565190, 2025). "As regards the pathological variables, there were high statistically significant differences between MTA1 expressions and the following variables: the histological type and grade of carcinoma, and the incidence of lymph vascular invasion (P < 0.000)." (PMID 40660330, 2025). "The NuRD (MTA1) complex influences cancer EMT by modulating E-cadherin expression, thereby promoting cancer invasiveness and metastasis." (PMID 39154024, 2024). "Our study aimed to explore the anticancer potential of Terminalia elliptica by identifying bioactive compounds capable of targeting FAK, VEGF, and MTA1 to impede cancer metastasis." (PMID 39355129, 2024). "Targeting these key proteins, MTA1, VEGF, and FAK, can significantly affect the pathways and underlying mechanisms contributing to cancer development and progression." (PMID 39355129, 2024). "Proteins, such as MTA1, play a significant role in regulating gene expression and facilitating cancer cell invasion and migration." (PMID 39355129, 2024). "MTA1 expression was positively correlated with cancer histological grade, whereas those of MTA3 and TRIM21 were the opposite." (PMID 39154024, 2024). "Recently, IDH3α has been found to promote the progression of HCC by inducing expression of metastasis-associated 1 (MTA1), an oncogene regulating cancer progression and metastasis." (PMID 37296846, 2023).
cancer (continued). "MTA1 is mainly studied in cancer, and it plays a role in the transformation, invasion, survival, DNA repair, angiogenesis, hormone dependence and treatment resistance of cancer." (PMID 36786127, 2023). "Previously, we reported that MTA1 is localized in the cytoplasm in cancer cells, but its detailed functions remain to be explored." (PMID 37442756, 2023). "In our previous research, we reported overexpression of MTA1 in the majority of cancer types, which contributes to the malignant phenotypes of cancers, especially metastatic behaviors." (PMID 35350571, 2022). "The obtained data showed that this compound stimulates autophagy in human liver cells, which modulates cancer cell metastasis by inhibiting WNT-CTNNB1/β-catenin pathway activity and decreasing MTA1 (metastasis-associated 1) expression." (PMID 36497321, 2022). "To illustrate the effect of MTA1 expression in cancer cells on the function of macrophages, we analyzed single-cell RNA-seq data from the GEO database." (PMID 35350571, 2022). "IDH3α promotes the upregulation of the expression of Metastasis Associated 1 (MTA1), an oncogene that stimulates epithelial-mesenchymal transition in HCC, which in turn induces cancer cell migration and invasion." (PMID 36497259, 2022). "The expression of MTA1 is correlated with the aggressive ability of many cancers, indicating that MTA1 is a potential cancer therapeutic target." (PMID 33953349, 2021). "Recently, MTA1-targeted chemopreventive agents for cancer therapy have been continuously developed and studied." (PMID 34502289, 2021). "In recent years, several studies have focused on MTA1 as an important mediator of cancer therapeutic resistance." (PMID 34502289, 2021). "In this case, MTA1 can control a spectrum of cancer-promoting processes, including transformation, proliferation, invasion, and metastasis, as well as angiogenesis." (PMID 34502289, 2021). "The MTA1-3 components of NuRD regulate invasive behavior in several cancers, with unique and often antagonistic activities." (PMID 34070411, 2021). "For example, tumor progression in many cancer types is observed when MTA1 expression is increased, while MTA3 limits breast tumor progression by repressing a master regulator." (PMID 34070411, 2021). "Together, these findings highlight the potential of using MTA1 as a promising therapeutic target and facilitating MTA1-targeted strategies, as well as developing combinatorial therapeutic approaches for cancer treatment in the future." (PMID 34502289, 2021). "In the last section, we focused on MTA1 (metastatic tumor antigen 1), a cancer-promoting molecule that we have studied extensively and is particularly overexpressed in HBV-HCC." (PMID 34502289, 2021). "Although this project is not being conducted for HCC, it still offers clinical proof for pterostilbene as a promising natural agent for MTA1-targeted chemopreventive and therapeutic strategies to curb cancer." (PMID 34502289, 2021). "Despite the fact that the role of MTA1 in therapeutic resistance has not been studied and discussed on HCC, these studies provide information about emerging functions and mechanisms of MTA1 in aggressive cancers." (PMID 34502289, 2021). "MTA1 is a cancer-promoting molecule and has attracted wide attention because of its interaction with HBx contributing to HCC development." (PMID 34502289, 2021). "The MTA1-fCLIP genes were enriched on cancer pathways, cell cycle, ubiquitin-mediated proteolysis, endocytosis, etc.." (PMID 32901005, 2020). "JMJD5 suppression markedly reduced cancer cell proliferation at least partly through the regulation of MTA1 signals." (PMID 32678829, 2020). "We next detected the correlation between MTA1 and mitotic defectiveness in clinical cancer specimens." (PMID 32901005, 2020). "RNA-related enrichment of MTA1’s function was largely attributed to its consistent correlation with numerous RBPs across different cancers (some examples are shown)." (PMID 32901005, 2020).
cancer (continued). "To explore the RNA binding-related role of MTA1 in cancer, we enriched the MTA1-fCLIP DEGs and RASGs using DAVID." (PMID 32901005, 2020). "The fact that most components of NuRD correlated significantly with MTA1 in the CCLE pan-cancer samples, verified that interacted molecules emerged in parallel at the transcriptional level." (PMID 32901005, 2020). "Here, we demonstrate MTA1, as an RNA-binding chromatin-associated protein (CAP), facilitates cancer development and progression by governing transcript abundance and AS pattern of mitosis regulators during mitosis." (PMID 32901005, 2020). "In the 180 cases of paired tissues, 0 (0%) were found with pathological mitosis in adjacent normal, while 141 (78.33%) in cancer, and the frequency of pathological mitosis in cancer increased with MTA1 intensity scaling-up (p < 0.001)." (PMID 32901005, 2020). "We found that IL-17 promoted migration and invasion of human cancer cells through upregulation of MTA1 expression." (PMID 31281798, 2019). "MTA1 is the first gene found in this family, which has been shown to be over-expressed in several human cancers, such as breast, stomach, and colorectal cancer." (PMID 31281798, 2019). "Due to its widespread overexpression in human cancers and its dual co-repressor and co-activator functions, MTA1 is considered a master regulatory molecule capable of regulating many pathways that are critical to cancer development and progression." (PMID 30782165, 2019). "MTA1 has emerged as one of several highly deregulated oncogenes in human cancer, possibly because of its dual nature as corepressor and coactivator." (PMID 31217897, 2019). "Phosphatase and tensin homolog deleted on chromosome 10 (PTEN), an anti-oncogenic gene, has been shown to be inactivated by MTA1 in malignant tumor cells." (PMID 30884859, 2019). "We also found that MTA1 was responsible for IL-17-induced migration and invasion of HeLa and DU-145 cells, as MTA1 knockdown abolished IL-17-induced migration and invasion of the cancer cells." (PMID 31281798, 2019). "MTA1 is a transcriptional co-regulator that can act as both a co-activator and co-repressor to regulate pathways that contribute to cancer development." (PMID 30782165, 2019). "MTA1 is also one of the most up-regulated proteins in cancer, whose expression correlates with cancer progression, poor prognosis and increased metastatic potential." (PMID 30782165, 2019). "In the present study, we found that IL-17 induced mRNA and protein expression of MTA1 in human HeLa and DU-145 cancer cells." (PMID 31281798, 2019). "Next, we checked if MTA1 plays any role in cancer cell invasion using Corning® BioCoatTM Matrigel® Invasion Chambers." (PMID 31281798, 2019). "Several studies have reported that MTA1 is also expressed at a low level in most normal cells but at significantly higher levels in most cancers." (PMID 30596107, 2018). "Overexpression of MTA1 has been observed in many tumors, such as breast, colorectal, gastric, and esophageal cancers." (PMID 30596107, 2018). "In particular, metastasis-associated protein 1 (MTA1) has been identified as an integral member of NuRD complexes, and it is associated with EMT during invasiveness of several types of cancers." (PMID 29888254, 2018). "Metastatic tumor antigen 1 (MTA1) is correlated with cancer aggressiveness and an increase in the migration and invasion of various human tumors by modulating the expression of target genes." (PMID 29334999, 2018). "Several studies have shown that MTA1 acts as an important upstream modifier of Wnt1 signaling in cancer cells." (PMID 29334999, 2018). "The underlying mechanism was closely associated with tetrandrine-induced human liver cell autophagy, which inhibits Wnt/β-catenin pathway activity and decreases metastatic tumor antigen 1 (MTA1) expression to modulate cancer cell metastasis." (PMID 29334999, 2018).